HSD17B10 (hydroxysteroid 17-beta dehydrogenase 10)
Diseases named in the same sentence as HSD17B10 in open-access papers:
HSD17B10 is named in the same sentence as 53 diseases in open-access papers, as found by Europe PMC text mining. Sharing a sentence is not in itself a finding about the gene and the disease. The quoted sentences say what the papers report.
Alzheimer disease (12 papers, 2006 to 2025). A progressive, neurodegenerative disease characterized by loss of function and death of nerve cells in several areas of the brain leading to loss of cognitive function such as memory and language. "HSD17B10 deficiency causes neurodegeneration in humans and has been associated with Alzheimer's disease." (PMID 26520658, 2015). "HSD17B10 may contribute to the neuronal dysfunction associated with Alzheimer disease (AD) by interacting with intracellular amyloid-beta (Aβ), and binding with Aβ can inhibit HSD17B10 activity." (PMID 32703935, 2020). "It is no longer appropriate to confound the literature by employing the misnomer ABAD because it frustrates the progress of critical work in the studies of HSD17B10-gene-related disorders, including Alzheimer’s disease and intellectual disabilities." (PMID 37239833, 2023). "The results demonstrated that acetylation is an important regulation mechanism for HSD17B10 and may provide insight into interrupting the development of Alzheimer disease." (PMID 32703935, 2020). "In Alzheimer disease (AD), HSD17B10 activity is inhibited by interacting with intracellular Aβ which may contribute to the neuronal dysfunction associated with AD17." (PMID 32703935, 2020).
Choreoathetosis (3 papers, 2011 to 2015). Involuntary movements characterized by both athetosis (inability to sustain muscles in a fixed position) and chorea (widespread jerky arrhythmic movements). "The syndromic form of mental retardation with choreoathetosis was shown to be associated with silent mutation in HSD17B10." (PMID 25637059, 2015).
Cognitive impairment (3 papers, 2012 to 2022). Abnormal cognition is characterized by deficits in thinking, reasoning, or remembering. "HSD17B10 mutations cause a rare inborn error of metabolism characterized by cognitive impairment and variable neurological abnormalities." (PMID 35347128, 2022).
HSD10 mitochondrial disease (3 papers, 2011 to 2021). A rare, life-threatening neurometabolic disease characterized by a progressive neurodegenerative course, epilepsy, retinopathy and progressive cardiomyopathy. "It is well established that HSD10 deficiency, formerly MHBD deficiency, resulted from a missense mutation in the HSD17B10 gene." (PMID 22132097, 2011). "HSD10 mitochondrial disease (HSD10MD; OMIM 300438) is a rare X‐linked metabolic disorder caused by pathogenic variants in the HSD17B10 (17‐beta‐hydroxysteroid dehydrogenase X) gene (OMIM 300256)." (PMID 31654490, 2019). "In addition, elevated excretion of urinary 2M3HB and TIG indicates not only BKTD but also HSD10 mitochondrial disease (HSD10MD, OMIM #300438), which is a rare X-linked recessive disorder caused by a hemizygous or heterozygous mutation in the HSD17B10 gene." (PMID 34001203, 2021).
intellectual disabilities (3 papers, 2011 to 2023). "Identification of a missense mutation in the HSD17B10 gene of the patient and his mother is necessary for diagnosing HSD10 deficiency, an X-linked intellectual disability." (PMID 22132097, 2011). "Duplication of the HSD17B10 gene also promotes idiopathic mental retardation." (PMID 22132097, 2011). "Studies on the properties of 17β-HSD10 are critical to the search for potential treatments of HSD17B10 gene-related disorders, including infantile neurodegeneration or HSD10 deficiency due to a missense mutation and intellectual disabilities caused by a silent mutation as well as a gene duplication." (PMID 38139430, 2023).
cardiomyopathy (2 papers, 2020 to 2024). A disease of the heart muscle or myocardium proper. "Mutation of HSD17B10 impairs mitochondrial RNA processing, disrupts respiratory chain complex function, and leads to neurodegeneration, cardiomyopathy, and early death." (PMID 32859923, 2020). "Mutations in the MRPP2/HSD17B10 protein cause progressive neurodegeneration, retinopathy and cardiomyopathy." (PMID 38779771, 2024).
colorectal cancer (2 papers, 2023 to 2025). A primary or metastatic malignant neoplasm that affects the colon or rectum. "In colorectal cancer, high HSD17B10 expression is associated with improved overall survival." (PMID 37907864, 2023). "Single-cell and spatial transcriptome data further demonstrated that HSD17B10 had a cell-type-specific expression pattern in colorectal cancer." (PMID 40427756, 2025). "Single-cell and spatial transcriptome data further demonstrated that HSD17B10 has a cell-type-specific expression pattern in colorectal cancer." (PMID 40427756, 2025). "This study analyzed HSD17B10’s role at the gene expression level and explored its cell localization in colorectal cancer using the GSE146771 dataset." (PMID 40427756, 2025). "This study also studied the spatial transcriptome of HSD17B10 in colorectal carcinoma." (PMID 40427756, 2025). "The HSD17B10 gene may influence colorectal cancer through cell cycle regulation." (PMID 40427756, 2025). "Recent studies, through the analysis of the coexpression network of HSD17B10 in bladder cancer (BLCA) and the analysis of the single-cell and spatial transcriptome of colorectal cancer (CRC), have further revealed the potential role of this gene in tumorigenesis and development." (PMID 40427756, 2025).
developmental delay (2 papers, 2018 to 2019). "A Caucasian boy with intractable epilepsy and global developmental delay carried a novel p.(Lys212Glu) mutation in the X-linked gene, HSD17B10 encoding for mitochondrial SDR5C1." (PMID 29980628, 2018). "In addition, a novel mutation in the MRPP2 encoding gene (X-linked gene, HSD17B10) was found to be causative of intractable epilepsy and global developmental delay." (PMID 31064115, 2019).
developmental disabilities (2 papers, 2013 to 2025). "HSD10 which is encoded by the HSD17B10 gene, has both enzymatic and non-enzymatic functions that are central to a number of developmental disabilities and AD." (PMID 23834306, 2013).
diabetes (2 papers, 2014 to 2025). "Further, MFHAS1 and IQGAP2 have some known association with diabetes or related disorders, whereas the other three genes: ZMYM3, HSD17B10 and ABCB7 have no known direct association with diabetes." (PMID 41462339, 2025).
glioma (2 papers, 2014 to 2022). A benign or malignant brain and spinal cord tumor that arises from glial cells (astrocytes, oligodendrocytes, ependymal cells). "Six genes of these essential TrMGs, including MAOB, HSD17B10, KYNU, AOX1, and OGDH, were determined as hazardous factors for glioma patients, and other two genes (CYP2E1 and ALDH2) were identified as protective factors." (PMID 36386216, 2022).
ulcerative colitis (2 papers, 2013 to 2014). An inflammatory bowel disease involving the mucosal surface of the large intestine and rectum. "The expression of the HSD17B10 gene was also significantly elevated in colonic mucosa of the inactive ulcerative colitis patients." (PMID 23834306, 2013). "Moreover, a significant change of HSD17B10 expression was found in the colonic mucosa of patients with ulcerative colitis." (PMID 23834306, 2013).
autism (1 paper, 2013). Persistent deficits in social interaction and communication and interaction as well as a markedly restricted repertoire of activity and interest as well as repetitive patterns of behavior. "Using chromosome microarray analysis, Edens and colleagues reported duplications involving Xp11.22-p11.23, a region where HSD17B10 gene is located, in two females with autism and epilepsy." (PMID 23697635, 2013).
breast carcinoma (1 paper, 2023). "For example, high intratumoural expression of HSD17B enzymes involved in E1 synthesis, such as HSD17B2, HSD17B10 and HSD17B14, are associated with lower OS and/or DMFS in ER+ breast cancer patients." (PMID 36674737, 2023).
endometrial carcinoma (1 paper, 2023). A malignant tumor arising from the epithelium that lines the cavity of the uterine body. "In addition, we also found an overexpression of the HSD17B10 enzyme in endometrial carcinomas of the uterine body compared to normal tissue." (PMID 36674737, 2023).
hepatocellular carcinoma (1 paper, 2022). A malignant tumor that arises from hepatocytes. "An interaction between Hsd17b10 and 14-3-3ε was inferred in hepatocellular carcinoma cells, but not confirmed." (PMID 36359893, 2022).
optic atrophy (1 paper, 2009). A disorder characterized by loss of optic nerve fibers. "For example, the optic atrophy 2 (OPA2) linkage interval contains seven mitochondrial genes that include three known DG of which HSD17B10 is associated with optic atrophy, and three predicted DG of which two genes (NDUFB11, TIMM17B) interact with mitochondrial DG causing optic atrophy." (PMID 19390613, 2009).
Parkinson disease (1 paper, 2018). A progressive degenerative disorder of the central nervous system characterized by loss of dopamine producing neurons in the substantia nigra and the presence of Lewy bodies in the substantia nigra and locus coeruleus. "Next we interrogated the KEGG pathway and found the top up-regulated categories showed strong correlation with Alzheimer’s, Huntington’s and Parkinson’s diseases by enriching genes such as ATP5D, ATP5H, HSD17B10 and NDUFB11, NDUFA8, NDUFB7, NDUFS8." (PMID 29915338, 2018).
pheochromocytoma (1 paper, 2023). "Overexpression of HSD17B10 in pheochromocytoma cells leads to abnormal cell growth in the laboratory and in the body, and high levels of HSD17B10 are linked to poor patient prognosis." (PMID 37907864, 2023).
prostate carcinoma (1 paper, 2023). A carcinoma that arises from epithelial cells of the prostate gland. "In prostate cancer, HSD17B10 is administered in combination with steroids and produces dihydrotestosterone in the absence of testosterone, which is a different way of producing androgens." (PMID 37907864, 2023).
prostate tumor (1 paper, 2013). "We however found high expression levels of certain steroidogenic enzymes; SRD5A1, AKR1C2, AKR1C3, and HSD17B10, in bone metastases when compared to non-malignant prostate and primary prostate tumor tissue." (PMID 24244276, 2013). "A similar shift from primarily HSD17B6 expression in non-malignant and primary prostate tumor tissue to mainly HSD17B10 expression in PC metastases was furthermore noted." (PMID 24244276, 2013).
viral diseases (1 paper, 2025). "By contrast, POR, CNTN2, and HSD17B10 have not previously been associated with viral diseases." (PMID 41303479, 2025).
tumor (10 papers, 2014 to 2025). "For example, in certain cancers, high expression of HSD17B10 is associated with tumor invasiveness and drug resistance, while low expression may indicate a better prognosis." (PMID 40427756, 2025). "Using GEPIA2 with TCGA tumor data, we obtained 30 genes highly linked to HSD17B10 expression." (PMID 40427756, 2025). "By clarifying the expression patterns of HSD17B10 in different cancers, targeted treatment plans are expected to be designed to inhibit its function in cancer cells, thus effectively suppressing tumor growth." (PMID 40427756, 2025). "This study also utilized MCPCOUNTER, IPS, TIMER, and EPIC algorithms to examine the relationship between immune cell infiltration levels and HSD17B10 expression in various tumor types from the TCGA database." (PMID 40427756, 2025). "Functional enrichment analysis revealed that HSD17B10 participated in tumor progression by regulating oxidative phosphorylation, mitochondrial metabolism, and RNA methylation." (PMID 40427756, 2025). "We also found that the enzyme HSD17B10 was overexpressed in tumour tissue compared to normal tissue." (PMID 36674737, 2023). "This study showed that the expression of HSD17B10 is significantly lower in paracancerous tissue than in tumor tissue and that the expression of HSD17B10 correlates with the pathological, T, and N stages of patients with THCA." (PMID 37907864, 2023). "Several enzymes related to androgen biosynthesis and (re-)activation were highly expressed in all tumor biopsy samples, including HSD17B10, STS, SRD5A1, AKR1C3, and HSD11B2." (PMID 33974560, 2021). "Different subtypes have diverse gene expression profiles, hormone receptor statuses, and tumor microenvironments, which could modulate the role of HSD17B10." (PMID 40427756, 2025). "Furthermore, the synergistic effects of HSD17B10 with RNA methylation regulators like m6A and m5C further support its involvement in tumor metabolic reprogramming via epigenetic networks." (PMID 40427756, 2025). "Moreover, HSD17B10 not only has a complex relationship with the tumor immune microenvironment, but also participates in the mitochondrial energy metabolism of tumor cells." (PMID 40427756, 2025). "HSD17B10 also had a two-way relationship with the tumor’s immune microenvironment." (PMID 40427756, 2025). "Since HSD17B10 links to immune-related genes in most tumors, it could be a potential tumor treatment target." (PMID 40427756, 2025). "Previous studies have confirmed HSD17B10’s link to tumor prognosis and immune response." (PMID 40427756, 2025). "Single-cell and spatial transcriptomic data further revealed cell-type-specific expression patterns of HSD17B10 in CRC, with dynamic changes observed in tumor and immune cells, providing new insights into its spatial heterogeneity." (PMID 40427756, 2025). "The link between HSD17B10 and the ESTIMATE score could assist in predicting the tumor immune microenvironment and patients’ treatment responses, laying a foundation for personalized treatment." (PMID 40427756, 2025). "Of the top 20 differentially expressed proteins identified in tumour samples, four (MDH2, FASN, EPCAM, and HSD17B10) are targetable by FDA-approved drugs, whereas two (AMACR and GLYATL1) are potentially targetable and are of potential interest for future research." (PMID 38052461, 2024). "Notably, TIPARP was highly expressed in the tumor relative to the normal group expression, and CD24, TACC1, HSD17B10, and CAV1 were less expressed in the tumor relative to the normal group." (PMID 37907864, 2023). "In general, proteins involved in fatty acid β-oxidation such as hydroxysteroid (17-beta) dehydrogenase 10 (HSD17B10), enoyl-CoA hydratase, short chain, 1, mitochondrial (ECHS1), enoyl-CoA delta isomerase 1 (ECI1) were down- regulated in tumour-bearing animals (p-value < 0.001)." (PMID 29258509, 2017).
tumor (continued). "Analysis of the interaction between HSD17B10 and the tumor immune microenvironment demonstrated that its expression positively correlated with ESTIMATE scores in GBM-LGG, LGG, and UVM, suggesting a potential role in promoting tumor progression through enhanced stromal and immune cell infiltration." (PMID 40427756, 2025).
cancer (4 papers, 2014 to 2024). A tumor composed of atypical neoplastic, often pleomorphic cells that invade other tissues. "When estradiol is oxidized to the weaker estrone, this estrogen is controlled using proteomic data and bioinformatics on thyroid tissue, and HSD17B10 was used to identify possible markers for thyroid follicular tumors and carcinomas." (PMID 37907864, 2023).
mitochondrial disease (4 papers, 2019 to 2025). "Pathogenic HSD17B10 gene variants cause HSD10 mitochondrial disease (HSD10 MD), which results in a wide spectrum of symptoms ranging from mild to severe." (PMID 40055822, 2025). "Pathogenic variants of the HSD17B10 gene cause HSD10 MD, whose clinical features are similar to those of severe mitochondrial diseases (progressive neurodegeneration, cardiomyopathy and metabolic disorders)." (PMID 40055822, 2025).
metabolic disease (2 papers, 2013 to 2025). A congenital disorder (due to inherited enzyme abnormality) or acquired (due to failure of a metabolically important organ) disorder resulting from an abnormal metabolic process. "Missense mutations of the HSD17B10 gene result in an X-linked metabolic disease in males while most females are asymptomatic." (PMID 23834306, 2013).
neurodegenerative disease (2 papers, 2013 to 2025). A disorder of the central nervous system characterized by gradual and progressive loss of neural tissue and neurologic function. "KEGG analysis showed that HSD17B10 was involved in disease-related metabolic pathways, and oxidative phosphorylation, with a high (Count) value, was important in energy metabolism and might link to neurodegenerative diseases." (PMID 40427756, 2025).
HSD17B10 also shares sentences with these, for which no sentence is quoted: infection (3 papers); type 2 diabetes (2); chronic allograft nephropathy (1); Cirrhosis (1); Crohn disease (1); Down syndrome (1); end-stage renal disease (1); epilepsy (1); fibrosarcoma (1); glomerulosclerosis (1); IgA glomerulonephritis (1); kidney nephropathy (1); kidney transplant (1); liver fibrosis (1); melanoma (1); neuroblastoma (1); neurodevelopmental disorder (1); Neurological Disease (1); Obesity (1); optic atrophy 2 (1); renal dysfunction (1); retinopathy (1); stomach cancer (1); thyroid cancer (1); X-linked disease (1); ZIKV infection (1).